CDK2 (cyclin dependent kinase 2)
Diseases named in the same sentence as CDK2 in open-access papers (continued):
Sharing a sentence is not in itself a finding about the gene and the disease.
melanoma (continued). "The RT–PCR results showed that compared to the control, the mRNA levels of cell cycle proteins, such as cyclin E1 and CDK2, were enhanced in PRPS1-overexpressing melanoma cells, but the mRNA level of P16 was inhibited." (PMID 36203561, 2022). "Our results showed that CRO15 directly decreases MELK kinase activity during in vitro kinase assay but also in intact melanoma cells, as indicated by the inhibition of NF-κB phosphorylation and some mitotic makers, such as Cyclin E, CDK1 or CDK2." (PMID 33431809, 2021). "Another interaction of MITF with the cell is suggested by the suppression of melanoma colony formation by MITF downregulation, which can be rescued by CDK2 overexpression." (PMID 34698095, 2021). "Specifically, genes upregulated or downregulated in response to UV radiation involve CDKN1C, CDK2, COL11A1, KIT, and IGF1R, the majority of which are identified as differentially upregulated in melanoma versus atypical tumor or nevus." (PMID 35052351, 2021). "We used the transcriptomic and clinical data from melanoma and glioblastoma patients of anti-PD1 or anti-CTLA4 therapy to predict the immunotherapy response of cohorts with different STAT3/CDK2/4/6 expression." (PMID 33668805, 2021). "Collectively, in our study, both carotenoid extract and nanoemulsion were effective towards inhibition of melanoma cells A375 via elevating cyclin A and cyclin B expressions and decreasing CDK1 and CDK2 expressions for cell-cycle arrest at the G2/M phase." (PMID 34685938, 2021). "At the transcriptional level, MITF controls genes involved in cell survival (BCL2, HIF1A, BCL2A1), migration (DIAPH1, MET) and proliferation (CDK2, TBX2, CDKN1B), providing important signals for growth of melanoma cells." (PMID 34289891, 2021). "The results of this study showed that the PI3K-Akt signaling pathway and the key genes CDK2, CDK4, KIT, and VWF promoted the proliferation and metastasis of melanoma, and they were significantly related to the prognosis of patients with melanoma." (PMID 34582363, 2021). "MITF also regulates some genes that are important for melanoma survival (e.g., BCL2), proliferation (e.g., CDK2) and metastatic potential (e.g., c-MET)." (PMID 33746605, 2021). "In peripheral blood, a gene signature of 15 differentially expressed genes, which includes MYC and CDK2, is predictive and prognostic to anti-CTLA4 immunotherapy treatment and 1 year overall survival in melanoma patients." (PMID 31820036, 2020). "We also identified PHA-793887, a novel and potent inhibitor of CDK2, CDK5 and CDK723 as a compound that affects differentiation of melanoma cells." (PMID 32231230, 2020). "Prognostic correlation analysis of cutaneous melanoma with molecular markers found that high expression of hsa-miR-500a-3p, CDK2 and POLR2A genes or low expression of hsa-miR-150-5p can significantly reduce OS in melanoma patients." (PMID 33313406, 2020). "Some of these DEGs had been investigated previously, including CDK2, AKT1 and KIT, which have been widely accepted as oncogenes in melanoma." (PMID 30385854, 2019). "For instance, dinaciclib is an inhibitor of CDK1, CDK2, CDK5, and CDK9, and is active in a broad range of cancer cell lines originating from leukemia, melanoma, osteosarcoma and pancreatic cancer." (PMID 31446060, 2019). "Optimized from the purine template of seliciclib, CCT068127 exhibits greater potency and selectivity against purified CDK2 and CDK9 and superior antiproliferative activity against human colon cancer and melanoma cell lines." (PMID 29063678, 2018).
melanoma (continued). "It has been reported that MITF regulates proliferation and apoptosis through CDK2 and BCL2 in melanoma cells." (PMID 29885053, 2018). "Among the different cancer types, melanoma‐derived cell lines exhibited the highest and most significant correlation (Pearson r = 0.8, Padj = 2.4 e−12) between MITF and CDK2 mRNA expression levels (Dataset EV6)." (PMID 29507054, 2018). "Overall, our orthogonal analyses point to CDK2 as a candidate whose inhibition overcomes inherent resistance to BRAFi and Hsp90i (driven by MITF) and their combination in melanoma." (PMID 29507054, 2018). "Importantly, our study sets a remarkable example of cancer plasticity that underlies melanoma primary resistance to drug therapies: upon BRAFi treatment, the resistance is accompanied by MAPK pathway activation, which triggers cell cycle progression and CDK2 activation." (PMID 29507054, 2018). "We then dosed melanoma cells with different concentrations of demethylzeylasteral (1, 5, 10 and 20 μM, DMSO was used as control) for 48 h; we found that CDK2 and Cycin E1 decreased in a dose-dependent manner." (PMID 29072681, 2017). "CDK4 was also part of the PC1, and CDK2 was part of the MITF and melanoma signature in the study of Tirosh and co-workers which is suggestive for a role of both kinases in this study." (PMID 27903987, 2017). "In a recent study, we documented by way of molecular targeting of the cell cycle regulator, CDK2, that VGP and MGP melanoma cells are highly vulnerable to interference with their progression through S phase." (PMID 23116066, 2012). "CDK2 and p21Cip1 are previously identified MITF target genes in melanoma cells and our data suggest that the melanoma susceptibility gene CDK4 is also an MITF target gene." (PMID 18628967, 2008). "In this study, we evaluated the effectiveness of the CDK4/6 inhibitor, palbociclib, the CDK2 inhibitor, PF-07104091, the dual CXCR1 and CXCR2 (CXCR1/2) antagonist, SX-682, and the combination of these inhibitors for effective treatment of melanoma in preclinical models." (PMID 40904502, 2025). "Although no preclinical studies in melanoma have been published to date evaluating the efficacy of a pan-CDK2/4/6 inhibitor or the combination of a CDK4/6 inhibitor with a CDK2 inhibitor, studies have explored the impact of CDK2 inhibition on melanoma growth control." (PMID 40282469, 2025). "First, we compared the expression of CDK2 in patients with advanced melanoma who responded to anti-PD-1 therapy and those who did not responded using publicly available dataset (GSE91061)." (PMID 40557162, 2025). "The highly supported results have shown that naringin-7-rhamnoglucoside from B. stenostachya could possibly target the genes involved in the progression of melanoma, specifically PIM1, MEK1, CDK2, and PDK1." (PMID 40649898, 2025). "Altogether, these data suggest that the addition of the CDK2 inhibitor to CDK4/6 and CXCR1/2 inhibitors not only reduces melanoma tumor cell viability and tumor growth more effectively in BRAFWTNRASWT melanoma cells but also results in a less immunosuppressive tumor immune microenvironment." (PMID 40904502, 2025). "It was found that the introduction of genistein caused melanoma cells arrest in G2 phase through the impairment of CDK1 dephosphorylation, but not that of CDK2." (PMID 38586368, 2024). "The results of real-time PCR and Western blot for mRNA and protein expression levels of cell cycle-related factors showed that in melanoma cells with NOD2 overexpression, Cyclin E1/D1 and CDK2/4 expression levels were downregulated while promoting P27 expression." (PMID 39353904, 2024). "Inhibition of CDK2 in melanoma cell lines has been shown to overcome their resistance to BRAF and Hsp90 inhibitors, while BUB1 has been identified as a novel target downstream of SIRT1 in melanoma." (PMID 38023136, 2023).
melanoma (continued). "Our findings suggest that cinobufagin may affect melanoma by arresting the cell cycle by inhibiting three protein tyrosine/serine kinases (EGFR, ERBB2, and CDK2)." (PMID 38348352, 2023). "Therefore, the significant reduction in the phosphorylation of H3 on Ser10 and the high phosphorylation levels of Cdk2 on Tyr15 in PEL- and EPI-treated melanoma cells suggested an arrest of melanoma cells in G1." (PMID 35877720, 2022). "The quinazolinone 5c triggered cell cycle arrest in the S phase in melanoma MDA-MB-435 cells and in the G2/M phase in glioblastoma SNB-75 cells suggesting that CDK2 could be the potential biological target for the newly synthesised congeners." (PMID 35139719, 2022). "In melanoma cells with or without BRAFV600E inhibitor resistance, inhibiting the expression of CDK2, CDK4, KIT, and VWF may become a new choice to inhibit the progression of melanoma." (PMID 34582363, 2021). "In the GSE32474 dataset, the expression levels of CDK2, CDK4, KIT, and VWF in the melanoma metastasis group were significantly higher than those in the melanoma primary focus group (t = 2.616, 2.244, 2.137, and 2.570, respectively; logFC = 1.206, 0.240, 1.573, and 0.168, respectively; p < 0.05)." (PMID 34582363, 2021). "High expression of CDK2 and POLR2A genes in melanoma patients significantly reduced OS." (PMID 33313406, 2020). "In addition, EGFR-STAT3, CDK2 and AXL/AKT signaling pathways play critical roles in BRAFi resistance in melanoma." (PMID 30400954, 2018). "These researches have told us that CDK2 would be a unique target rather than other CDKs in melanoma therapy." (PMID 25045703, 2014). "Exogenous CDK2, osteopontin, or IGF1 each alone partly relieved the block of proliferation imposed by BRG1 depletion, implicating that more factors, besides the MITF target genes, are involved in melanoma cell survival." (PMID 23349796, 2013). "We identified the G1/S transition regulatory network with key pro-S phase genes (E2F, CCNE, CDK2, Cdc25A) induced in HBECs, but repressed or not regulated in melanoma cells." (PMID 22140489, 2011). "We also evaluate the addition of the CDK2 inhibitor, tagtociclib (PF-07104091), to this treatment regimen and assess whether this triple- drug combination results in greater inhibition of tumor growth in the B16F10 mouse model of melanoma." (PMID 40904502, 2025). "The derivatives of 4-benzoylamino-1H-pyrazole-3-carboxamide were recently shown as a potent CDK2 inhibitor that exhibited the highest anti-proliferative activities against cancer cell lines (e.g., A2058 melanoma and MV4-11 leukemia cell line) when compared to non-transformed human normal cell lines." (PMID 34641324, 2021). "In another report, resistance in melanoma patients was discovered following the use of the combination of the Hsp90 inhibitor XL888 with the BRAF inhibitor vemurafenib, but the use of dinaciclib as a CDK2 inhibitor abolished the resistance of patients to the combination." (PMID 32397330, 2020). "Dinaciclib targeted melanoma cell lines regardless of cdk2 or MITF levels." (PMID 23527225, 2013). "And although a crosstalk between Cdk2 and C-MYC was implicated in C-MYC induction and maintenance of senescence, C-MYC target genes responsible for continuous suppression of senescence in melanoma cells were not identified." (PMID 23249808, 2012). "Importantly, MITF depletion in melanoma cells blocked CDK2, p21Cip1 and CDK4 expression even though ERK was not inhibited." (PMID 18628967, 2008).
melanoma (continued). "For example, early-stage melanomas often express high levels of the immune modulator CD24 and the transcription factor GATA3, whereas progressed melanomas exhibit upregulation of the melanoma antigen family A (MAGE) antigens of unknown function, and cell cycle regulators such as CDK2." (PMID 19949544, 2009). "These synthetic small molecules were investigated as new, potential single and/or multi-kinase inhibitors of the cyclin-dependent kinase-2 (CDK2), receptor tyrosine kinases (c-KITs), and mammalian targets of rapamycin (mTOR) targets, potentially active against melanoma or non-melanoma skin cancers." (PMID 33665254, 2021). "In agreement with our earlier observation, we found that the expression of CDK2/4/6 shows a negative correlation with cytotoxic lymphocyte infiltration (CTL) in both GBM and melanoma, while STAT3 shows a negative correlation with CTL infiltrations in GBM but a positive correlation in melanoma." (PMID 33668805, 2021). "Cyclin E/CDK2 complexes (which are not inhibited by p16), like cyclin D-CDK4/6 complexes, can phosphorylate and inactivate pRb, and both human melanomas and DLBCLs expressing high-level p16 have been reported to escape p16 repression by activating cyclin E expression." (PMID 30125329, 2018). "However, depletion of cdk2 showed severe S-phase defects in several human cell lines (HeLa [cervical carcinoma], NCI-H1299 [non-small cell lung carcinoma], A375 & SKMEL5 [both melanoma]) but not in others (SW480 and HT-29 [both colon carcinoma])." (PMID 23555285, 2013). "In our melanoma cellular model, non significant differences were observed in p27pT187 levels after ROS modulation, both by addition or scavenging of H2O2, which is consistent with the fact that no variations were observed on cyclin E and CDK2 levels after catalase treatment." (PMID 22970236, 2012).
colon carcinoma (88 papers, 2009 to 2026). "These are also known to inhibit the production of cyclin‐dependent kinase 2 and cyclin B1, two proteins that are related to an enhanced risk of colon cancer." (PMID 40078339, 2025). "To elucidate the mechanisms underlying the constant expression of CDK2, 4, and 6, we initially searched for compounds that induce G1 cell cycle arrest in human colon cancer HT-29 and SW480 cells." (PMID 35681048, 2022). "Collectively, these results suggested that α-hederin reduced viability and arrested cell cycle associated with downregulation of cyclin B1 and CDK2 in colon cancer cells." (PMID 30363706, 2018). "Low-to-moderate CDK2 expression is related to the risk of colon cancer, although CDK2 activity above a certain threshold may also pose a risk." (PMID 31223310, 2019). "Cyclokinase B1 and cyclin‐dependent kinase 2 promote colon cancer; when colon cancer cells reach the G2/M phase, punicalagin induces apoptosis by inhibiting the action of these proteins." (PMID 40018013, 2025). "It has been reported that BA treatment in the colon cancer cell line HCT-116 caused a decrease in cyclin-dependent kinases such as cyclin D, cyclin E, CDK2 and CDK4." (PMID 40142291, 2025). "The CDK1/CDK2 inhibitors puruvanol A and roscovitine induce cell death in colon cancer cells and increase SSAT-1 levels." (PMID 37759783, 2023). "In fact, previous reports have confirmed that the expression of CDK2 is dramatically increased in various colon cancer cell lines, including HCT-116, HCT-15, LoVo and DLD-1, compared with “normal” human colon epithelial cells (HCECs)." (PMID 35890189, 2022). "This study created an insight for understanding the mechanistic studies on homologues series of N-alkyl (methyl, ethyl, propyl, isopropyl) tetrahydropyridinyl aurones against anticancer target CDK2/Cyclin A in colon cancer." (PMID 36065423, 2022). "Based on this rationale, we analyzed the protein levels of CDK2/4 and cyclin D1/E in colon cancer cells." (PMID 33669811, 2021). "After GSPT1 was silenced, the expression of GSK-3β, p21, and p27 increased, and the expression of CyclinD1, CDK4/6, cyclinE, and CDK2 decreased; these changes affected the progression of colon cancer cells from G1 phase to S phase and blocked the cell cycle." (PMID 33819920, 2021). "Cho and Park attributed the apoptogenic effects of kaempferol in HT-29 human colon cancer cells to the suppression of protein expression of CDK2." (PMID 32093300, 2020). "After transfection of the HINT1 WT or 2KR construct into the A375 colon cancer cell line, the association of HINT1 with MITF and the endogenous expression levels of MITF target genes, including tyrosinase and CDK2, were investigated." (PMID 32636443, 2020). "Silymarin, a natural flavonoid, showed its potent cancer chemopreventive efficacy against HT-29 Human colon cancer cells with inhibition in CDK2 kinase activity." (PMID 32093300, 2020). "SFN also induced a G2/M phase arrest in colon cancer cells, accompanied by an elevation of cyclin A, cyclin B, and Cdk2, but decreased Cdk1 protein expression." (PMID 33218199, 2020). "In our study, we found that NPTX1 inhibits cell proliferation by inducing cell cycle arrest and down-regulating cycle-related proteins (Cyclin A2 and CDK2), these findings are consistent with findings in colon cancer." (PMID 31113871, 2019). "For example, the expression of NPTX1 is down-regulated in colon cancer and inhibits cell proliferation via the down-regulation of Cyclin A2 and cyclin-dependent kinase 2 (CDK2) expression." (PMID 31113871, 2019). "In the present study, we demonstrated that MUM256 EA reduced the proliferation of colon cancer cells by arresting cells at G1 and G2 phases through the modulation of cell-cycle regulatory proteins including p21, cyclin B1, CDK2, CDK4 and cdc25A phosphatase." (PMID 31698795, 2019).